DCPS (decapping enzyme, scavenger)
Description:
Decapping scavenger enzyme that catalyzes the cleavage of a residual cap structure following the degradation of mRNAs by the 3'->5' exosome-mediated mRNA decay pathway. Hydrolyzes cap analog structures like 7-methylguanosine nucleoside triphosphate (m7GpppG) with up to 10 nucleotide substrates (small capped oligoribonucleotides) and specifically releases 5'-phosphorylated RNA fragments and 7-methylguanosine monophosphate (m7GMP). Cleaves cap analog structures like tri-methyl guanosine nucleoside triphosphate (m3(2,2,7)GpppG) with very poor efficiency. Does not hydrolyze unmethylated cap analog (GpppG) and shows no decapping activity on intact m7GpppG-capped mRNA molecules longer than 25 nucleotides. Does not hydrolyze 7-methylguanosine diphosphate (m7GDP) to m7GMP. May also play a role in the 5'->3 mRNA decay pathway; m7GDP, the downstream product released by the 5'->3' mRNA mediated decapping activity, may be also converted by DCPS to m7GMP. Binds to m7GpppG and strongly to m7GDP. Plays a role in first intron splicing of pre-mRNAs. Inhibits activation-induced cell death.
Synonyms: HINT-5; DCS1; HINT5; HSPC015; HSL1; DCS-1; ARS
Tractability: Small molecule: a structure with a bound ligand is known; a high-quality ligand is known; it has a high-quality binding pocket; it belongs to a druggable protein family. PROTAC: ubiquitination databases record sites on it; its protein half-life has been measured; a small molecule that binds it is known.
Target class: Enzyme; Hydrolase
Gene: Protein-coding gene on chromosome 11 (126,304,047 to 126,350,005, forward strand). Ensembl gene ENSG00000110063.
Subcellular location: Cytoplasm; Nucleus
Subcellular location (Human Protein Atlas): Nucleoplasm; Cytosol
Pathways (Reactome):
Metabolism of RNA: mRNA decay by 3' to 5' exoribonuclease
Gene Ontology:
Molecular function: 5'-(N(7)-methyl 5'-triphosphoguanosine)-[mRNA] diphosphatase activity; identical protein binding; protein binding; RNA 7-methylguanosine cap binding; RNA exonuclease activity; hydrolase activity
Biological process: mRNA cis splicing, via spliceosome; mRNA methylguanosine-cap decapping; deadenylation-dependent decapping of nuclear-transcribed mRNA; nuclear-transcribed mRNA catabolic process, deadenylation-dependent decay
Cellular component: cytoplasm; cytosol; m7G(5')pppN diphosphatase complex; nucleoplasm; nucleus; perinuclear region of cytoplasm; P-body
Genetic constraint (gnomAD): Loss-of-function variants: 27 observed, 37.22 expected, observed/expected ratio (o/e) 0.73, 90% interval 0.53 to 1. The upper end of that interval is the gene's LOEUF score, 1, which puts it in group 4 of 6, group 1 being the genes least tolerant of losing a copy. Missense variants: 464 observed, 457.22 expected, observed/expected ratio (o/e) 1.01, 90% interval 0.94 to 1.1. Synonymous variants: 185 observed, 196.41 expected, observed/expected ratio (o/e) 0.94, 90% interval 0.83 to 1.06.
Homologues: Orthologues: chimpanzee DCPS (99% identical), macaque DCPS (95% identical), pig DCPS (90% identical), mouse Dcps (90% identical), rat Dcps (89% identical), dog DCPS (88% identical), guinea pig DCPS (87% identical), tropical clawed frog dcps (60% identical), zebrafish dcps (53% identical), Drosophila melanogaster Dcps (39% identical), Caenorhabditis elegans dcs-1 (36% identical).
Diseases named in the same sentence as DCPS in open-access papers:
DCPS is named in the same sentence as 24 diseases in open-access papers, as found by Europe PMC text mining. Sharing a sentence is not in itself a finding about the gene and the disease. The quoted sentences say what the papers report.
acute myeloid leukemia (5 papers, 2019 to 2025). Acute myeloid leukemia (AML) is a group of neoplasms arising from precursor cells committed to the myeloid cell-line differentiation. "DCPS is very essential for acute myeloid leukemia cell survival by interacting with pre-mRNA." (PMID 31576243, 2019). "DcpS has recently been identified as an essential gene for acute myeloid leukemia (AML) cell survival through genome-wide CRISPR–Cas9 knockout screening." (PMID 40804482, 2025). "Recently, the pyrophosphatase DCPS (Decapping scavenger enzyme) was identified and validated as a potential therapeutic target in Acute Myeloid Leukemia (AML), demonstrating that pharmacological inhibition of DCPS is detrimental for AML cells but dispensable for normal haematopoiesis." (PMID 40571744, 2025). "DcpS has also been shown to be essential for the survival of acute myeloid leukemia (AML) cells." (PMID 33833335, 2021). "For example, the mRNA decapping enzyme scavenger (DCPS) gene, which is essential for acute myeloid leukemia (AML) survival, thus allowing treatment of AML with RG3039, a DCPS inhibitor used to treat spinal muscular atrophy." (PMID 33014853, 2020).
spinal muscular atrophy (5 papers, 2015 to 2025). A motor neuron disease that affect the muscles, and characterized by muscle weakness and atrophy resulting from progressive degeneration and irreversible loss of the anterior horn cells in the spinal cord (i.e., lower motor neurons) and the brain stem nuclei. "Small molecules targeting DCPS have been employed in early trials for spinal muscular atrophy (SMA), and more recent development of proteolysis targeting chimeras (PROTACs) targeting DCPS may hold future promise as a therapeutic in AML." (PMID 39316554, 2024).
glioma (4 papers, 2022 to 2025). A benign or malignant brain and spinal cord tumor that arises from glial cells (astrocytes, oligodendrocytes, ependymal cells). "Moreover, the variance in expression levels of DCPS, EIF4E1B, NUDT1, and NUDT16L1 between glioblastomas (GBMs) and low-grade gliomas (LGGs) suggests their involvement in the progression of glioma malignancy." (PMID 39061374, 2024).
breast carcinoma (3 papers, 2022 to 2025). "Our results showed that SNP, rs1695739 in DCPS is one of the significant variants in our breast cancer patients." (PMID 36268271, 2022). "The results showed that the expression levels of AGO2 and EIF4E3 were significantly lower in breast cancer cell lines than in the normal breast cell line, whereas the expression levels of DCPS and EIF4E were significantly higher." (PMID 37353728, 2023). "Our exome wide biomarkers study identified 4 SNPs [SNRK and SNRK-AS1-rs202018563G; BRCA2-rs2227943C; ZNF484-rs199826847C; and DCPS-rs1695739G] as the most significant SNPs among our patients with breast cancer compared to the healthy controls." (PMID 36268271, 2022). "Breast cancer cell lines (MDA-MB-231, MDA-MB-468 and SKBR3) and a normal breast cell line (MCF-10A) were used to validate the expression levels of the signature m7GRGs (AGO2, EIF4E3, DCPS and EIF4E)." (PMID 37353728, 2023).
Intellectual disability (3 papers, 2018 to 2025). "Biallelic mutations in the DCPS gene disrupting the decapping activity of the scavenger decapping protein DcpS, leads to neurodevelopmental deficiencies and intellectual disability." (PMID 40410278, 2025). "Indeed, mRNA decapping has already been associated with ID, as variants in the scavenger decapping enzyme (DCPS), which is responsible for decapping in the 3′ to 5’ mRNA decay pathway, were identified in several unrelated patients who have intellectual disability." (PMID 29685133, 2018). "DcpS plays general roles in the control of gene expression and has been independently linked to SMA, intellectual disability, and AML." (PMID 33833335, 2021).
neuroblastoma (2 papers, 2017). Neuroblastoma (NB) is the most common solid, extracranial childhood tumor. "In order to more broadly characterize the effects of DcpS inhibition on the transcriptome, N2a mouse neuroblastoma cells were treated for 24 hours with either 1 μM RG3039, 1 μM PF-06802336 or an equivalent concentration (1 μM) of DMSO vehicle." (PMID 28945765, 2017). "In SH-SY5Y neuroblastoma cells, DcpS knockout or treatment with D157495 increased the mRNA levels of ATOH7 as well as the putative lncRNAs DRNT1 and DRNT2." (PMID 28662219, 2017).
cognitive disorder (1 paper, 2025). A disease affects cognitive processes. "Importantly, a causal link has been established between mutations in the DCPS gene encoding the DcpS protein in neurodevelopmental and cognitive disorders that could also include microcephaly, musculoskeletal and craniofacial abnormalities collectively referred to as Al-Raqad syndrome." (PMID 40410278, 2025). "Moreover, supplementation of DcpS mutant patient cells with Cr reversed the decreased neuronal differentiation and neurite elongation, indicating the modulation of Cr may underly the neurogenesis defect in DcpS mutant cells and may be a contributor to the cognitive defects in affected individuals." (PMID 40410278, 2025).
Hypertension (1 paper, 2018). The presence of chronic increased pressure in the systemic arterial system. "The mechanism of FAM110A, PREP, ANKRD9, DCPS, WFDC12, TPTE, and LAMB2 genes on the occurrence and development of hypertension is not yet clear." (PMID 29379041, 2018).
liver cancer (1 paper, 2023). An epithelial or non-epithelial malignant neoplasm that arises from the liver. "Among the genes associated with the prognosis of liver cancer, the genes associated with shorter survival period are AGO2, DCPS, IFIT5, LARP1, NCBP2, NUDT10, and NUDT16; the genes associated with longevity are EIF4E3, EIF4G3, METTL1, NCBP1, NSUN2, NUDT11, NUDT4, and WDR4." (PMID 36845384, 2023).
viral infection (1 paper, 2020). "Interestingly, the role of XRN1 and DCPs in viral infections varies greatly." (PMID 32034313, 2020).
tumor (11 papers, 2022 to 2025). "The m7GRGs AGO2, EIF4E3, DCPS and EIF4E have been extensively studied, and some of them have been associated with tumour progression." (PMID 37353728, 2023). "Notably, DCPS manifested pronounced expression in both neoplastic and non‐neoplastic tissues, while DCP2, NCBP2, WDR4, and NUDT3 demonstrated intermediate expression across tumor and normal samples." (PMID 40485623, 2025).
infection (6 papers, 2012 to 2025). The state of being infected such as from the introduction of a foreign agent such as serum, vaccine, antigenic substance or organism. "Despite these previous reports, the broad antiviral role of XRN1 and DCPs during infection of cytoplasmic-replicating RNA viruses remains elusive." (PMID 32034313, 2020). "Mechanistically, infection with RNA viruses induced the enrichment of XRN1 and DCPs in viral replication complexes (vRCs), hence forming distinct cytoplasmic aggregates." (PMID 32034313, 2020). "We found that infections with RNA viruses from different families, including NDV, EMCV, Sendai virus (SeV), and vesicular stomatitis virus (VSV), trigger the aggregation of XRN1 and DCPs into distinct subcellular compartments containing viral ribonucleoproteins." (PMID 32034313, 2020). "A previous study reported the antiviral activity of the cellular XRN1–DCP1/2 complex and revealed that infection with RNA viruses enriches XRN1 and DCPs in viral RCs; this phenomenon is not correlated with the essential localization and function of PBs." (PMID 39972499, 2025).
cancer (4 papers, 2015 to 2023). A tumor composed of atypical neoplastic, often pleomorphic cells that invade other tissues. "A deregulation of DcpS expression as well as mutations could be a potential cause of the variation in miRNAs profiles observed in cancer." (PMID 26584588, 2015). "In addition, m7G genes such as EIF4E2, DCPS, WDR4, and METTL1 were highly correlated with RARA-AS1 in multiple types of cancer (greater than 10 types)." (PMID 37833349, 2023). "In addition, we also explored the expression of AGO2, EIF4E3, DCPS and EIF4E in pan-cancer." (PMID 37353728, 2023).
neurodevelopmental disorder (1 paper, 2025). A behavioral and cognitive disorder with onset during the developmental period that involves impaired or aberrant development of intellectual, motor, or social functions. "Our study provides significant insights into the molecular mechanisms underlying the neurodevelopmental disorders associated with the DcpS splice site mutation (c.636 + 1G > A)." (PMID 40410278, 2025). "In conclusion, our study elucidates the underpinnings of the neurodevelopmental disorder associated with the DcpS splice site mutation and identifies the Cr biosynthetic pathway as at least one critical contributor to the underlying neurodevelopmental defect." (PMID 40410278, 2025).
DCPS also shares sentences with these, for which no sentence is quoted: Autoimmunity (1 paper); bone osteosarcoma (1); brain malformation (1); colorectal cancer (1); congenital heart disease (1); gastric cancer (1); glioblastoma (1); leukemia (1); melanoma (1); microcephaly (1).